TGIF2-RAB5IF (TGIF2-RAB5IF readthrough)
Synonyms: TGIF2-C20orf24
Gene: Protein-coding gene on chromosome 20 (36,574,553 to 36,612,384, forward strand). Ensembl gene ENSG00000259399.
Genetic constraint (gnomAD): Loss-of-function variants: 13 observed, 23.9 expected, observed/expected ratio (o/e) 0.54, 90% interval 0.35 to 0.87. The upper end of that interval is the gene's LOEUF score, 0.87, which puts it in group 3 of 6, group 1 being the genes least tolerant of losing a copy. Missense variants: 163 observed, 196.59 expected, observed/expected ratio (o/e) 0.83, 90% interval 0.73 to 0.94. Synonymous variants: 75 observed, 81.01 expected, observed/expected ratio (o/e) 0.93, 90% interval 0.77 to 1.12.